MAT2A (methionine adenosyltransferase 2A)
Diseases named in the same sentence as MAT2A in open-access papers (continued):
Sharing a sentence is not in itself a finding about the gene and the disease.
breast carcinoma (continued). "Furthermore, cytoplasmic MAT2A was upregulated in breast cancer tissues compared with normal breast tissues (p < 0.001)." (PMID 34065390, 2021). "MAT2A C/N expression ratio determined by IHC staining could serve as a novel independent prognostic marker for breast cancer." (PMID 34065390, 2021). "MAT2A protein is involved in methyl donor production and was previously found to have a dynamic nuclear localization, and whether MAT2A protein localization may influence breast cancer development is unknown." (PMID 34065390, 2021). "Future studies on how MAT2A localization may modulate breast cancer development and progression are warranted." (PMID 34065390, 2021). "The modulation of MAT2A subcellular localization and function may serve as a potential novel therapeutic strategy for breast cancer." (PMID 34065390, 2021). "Since the actual distributions and localizations of MAT2A protein cannot be determined in RNA-seq data, we further investigated the prognostic potential of MAT2A protein distributions and localizations in our own breast cancer cohort using tissue array." (PMID 34065390, 2021). "The previous in vitro finding of MAT2A translocation in cancer cell lines as well as our findings on MAT2A mRNA and breast cancer survival inspired us to explore the prognostic potential and the clinical application of the subcellular localization of MAT2A in our breast cancer cohort study." (PMID 34065390, 2021). "However, regulation of MAT2A expression in TAM-resistant breast cancer and its roles in tumor growth and chemoresistance have been uncovered." (PMID 26418898, 2016). "Moreover, we assessed the expression level of MAT2A in human breast cancer tissues by immunohistochemistry." (PMID 26418898, 2016). "We recently discovered that MAT1A and GNMT were mostly expressed in the cytoplasm, whereas MAT2A showed both cytoplasmic and nuclear immunoreactivity, and that a higher cytoplasmic/nuclear (C/N) MAT2A expression ratio is correlated with poor overall survival in breast cancer patients." (PMID 35008908, 2022). "Hence, it is plausible that the elevated TNF-α partially accounts for the induction and overexpression of MAT2A in breast cancer, and there could be a link between inflammation and MAT2A expression during breast cancer progression." (PMID 34065390, 2021). "To investigate MAT2A subcellular localization in human breast cancer cells and explore whether they are potentially involved in cancer cell invasion, we compared the MAT2A protein levels in the cytoplasm and nucleus as well as the invasiveness in a panel of breast cancer cell lines." (PMID 34065390, 2021). "Despite the potential regulatory role of MAT2A translocation in tumor development, whether MAT2A distribution affect in breast cancer progression is unknown, thus we aimed to explore the relationship between MAT2A distribution and breast cancer clinical indicators." (PMID 34065390, 2021). "Therefore, miR-146b decrease and MAT2A induction could be new phenotypes contributing to the growth of breast cancer cells and tamoxifen resistance in breast cancer cells." (PMID 26418898, 2016). "The lncRNA PARTICLE controls the expression of tumor suppressors MAT2A and WWOX in breast cancer and osteosarcoma respectively." (PMID 34207434, 2021). "The present study demonstrated a novel strategy that used the MAT2A C/N ratio rather than the MAT2A expression for breast cancer prognosis." (PMID 34065390, 2021). "No statistical difference was found in nuclear MAT2A expression between normal and breast cancer tissues." (PMID 34065390, 2021). "Increased MAT2A and MAT2B expression occurs in human liver and colon cancers and increased MAT2A expression has also been reported in human gastric cancer and tamoxifen-resistant breast cancer cells." (PMID 29108270, 2017). "However, MAT2A has not been elucidated in breast cancer prognosis." (PMID 34065390, 2021).
colon cancer (14 papers, 2006 to 2025). "Methionine adenosine transferase 2 A (MAT2A) encodes MATα2, which is highly expressed in colon cancer and regulated by the SUMOylation of SUMO1, SUMO2 and SUMO3." (PMID 37777749, 2023). "In the same way, MAT2A expression in human colon cancer resections, mice polyps and cell lines were increased, correlating with epidermal growth factor (EGF), insulin-like growth factor (IGF)-I and leptin-induced proliferation." (PMID 39941901, 2025). "In in vitro growing human colon cancer cells MAT2A is overexpressed, its inhibition by SAM and MTA blocks the growth." (PMID 35159219, 2022). "Outside of the liver, MAT2A and SAM expression has been reported in activated T lymphocytes and in human colon cancer cells where MAT2A expression is required for mitogen-induced cell growth." (PMID 26418898, 2016). "p65 knockdown reduces the basal level of MAT2A expression and blocks the additive effect of IGF-1 on MAT2A in human colon cancer cells." (PMID 26418898, 2016). "Specifically, Ubc9 and MAT2A expression are increased in both liver and colon cancers and SAMe, which lower both Ubc9 and MAT2A expression, induces apoptosis in these cancer cells." (PMID 26416353, 2015). "Exogenous SAMe decreases Ubc9 and MAT2A expression and is pro-apoptotic in liver and colon cancer cells." (PMID 26416353, 2015). "We also reported SAMe treatment lowered MAT2A expression and is pro-apoptotic in liver and colon cancer cell lines." (PMID 26416353, 2015). "Human liver and colon cancers have higher MAT2A expression, which is essential for growth as silencing MAT2A by sequence-specific small interfering RNA (siRNA) inhibited growth and induced apoptosis." (PMID 26416353, 2015). "MAT2A expression is increased in human colon cancer tissues and cells treated with mitogens, whereas silencing MAT2A resulted in apoptosis." (PMID 26416353, 2015). "Recent studies have illustrated there are abnormal expressions of MAT2A in some tumors, including liver, gastric and colon cancers." (PMID 24636201, 2014). "Several studies have demonstrated that there are abnormal expressions of MAT2A in several kinds of cancers such as liver and colon cancers." (PMID 24636201, 2014). "An increasing number of studies have suggested that MAT2A plays an important pathogenetic role in facilitating liver and colon cancer growth." (PMID 24636201, 2014). "MAT2A overexpression in liver and colon cancer increases tumor survival and chemo-resistance, by a mechanism involving B-cell lymphoma 2 (BCL-2) transcription, acting directly as a transcription factor that transactivates the BCL-2 promoter, and also stabilizing the BCL-2 protein." (PMID 39941901, 2025). "Among them, MAT2A and SNRPA were found to be involved in cell growth, with studies showing increased MAT2A expression in human colon cancer being implicated in the pathogenesis of colon cancer." (PMID 31581454, 2019). "Although MAT2A and MAT2B expression are induced in parallel in liver and colon cancers, the underlying mechanism that may connect them has remained unclear." (PMID 29108270, 2017). "MAT2A expression is linked to increased growth and cancer cell survival, while high MAT2B expression is linked to increased activity of RAS-RAF-MEK-ERK in colon cancer cells." (PMID 29108270, 2017). "Induction of MAT2A has also been correlated with disease progression in colon cancer." (PMID 16569247, 2006). "Furthermore, human liver and colon cancers are reported to have higher MAT2A expression." (PMID 39838121, 2025). "Elevated MAT2A and SAM levels are observed in murine colon cancer models and polyps, where growth factors (EGF, IGF-1, leptin) upregulate MAT2A to promote CRC cell growth." (PMID 41488637, 2025). "Accordingly, MAT2A up-regulation confers a growth advantage to human HCC and colon cancer as well as leukemic cells, and its downregulation by specific siRNA inhibits BrdU incorporation and induces apoptosis in RKO adenocarcinoma and HepG2 hepatoblastoma cells." (PMID 31073374, 2019).
gastric cancer (12 papers, 2017 to 2025). A primary or metastatic malignant neoplasm involving the stomach. "Recent studies have shown that the inhibition of MR or the SAM-generating enzyme Met adenylyltransferase 2A (MAT2A) results in gastric cancer cells that are more susceptible to iron apoptosis." (PMID 38397398, 2024). "Another mechanism for MAT2A-mediated gastric cancer progression involves the regulation of anti-inflammatory functions of tumor-associated monocytes." (PMID 39941901, 2025). "The activation of MAT2A expression in gastric cancer protects tumoral cells from ferroptosis, by increasing methylation of histone H3 of acyl-CoA synthetase long chain family member 3 (ACSL3) promoter in a SAMe-dependent manner." (PMID 39941901, 2025). "In gastric cancer, the enzyme methionine adenosyltransferase 2A (MAT2A) enhances the production of the methylation donor SAM, which increases the levels of H3K4me3 at the promoter of ACSL3, subsequently inhibiting ferroptosis." (PMID 39595619, 2024). "Overexpression of MAT2A has been shown in gastric cancer, and silencing of the MAT2A gene induces apoptosis and blocks cell cycle progression." (PMID 34258296, 2021). "Additionally, in gastric cancer, methionine adenosyltransferase 2A (MAT2A) promoted the production of the methylation donor SAM, which upregulated ACSL3 by increasing H3K4me3 abundance at the promoter, sequentially inhibiting ferroptosis." (PMID 37229485, 2023).
lymphoma (6 papers, 2020 to 2025). A malignant (clonal) proliferation of B- lymphocytes or T- lymphocytes which involves the lymph nodes, bone marrow and/or extranodal sites. "AG-270 is the first-in-class oral selective MAT2a allosteric inhibitor and is currently being tested in clinical trials for lymphoma and solid tumors." (PMID 40015640, 2025). "Currently there is a phase I clinical trial investigating the MAT2A inhibitor AG-270 in advanced solid tumors or lymphomas with homozygous deletions of CDKN2A/B or MTAP (NCT03435250)." (PMID 38017560, 2023). "Strikingly, we discovered the highest levels of MAT2A expression in brain cancer, leukemia, and lymphoma." (PMID 32456310, 2020). "In the meantime, AG-270, another MAT2A inhibitor with high affinity, has been developed that is already undergoing a phase I clinical trial in patients suffering from lymphoma or solid tumors (NCT03435250, clinical trials.gov), supporting the rationale to target MAT2A in leukemia." (PMID 32456310, 2020). "At present, a phase I clinical trial of MAT2A inhibitor AG-270 (NCT03435250) is ongoing for patients with advanced or refractory solid tumors and lymphomas." (PMID 34234122, 2021).
cervical cancer (5 papers, 2020 to 2023). A primary or metastatic malignant neoplasm involving the cervix. "Other targets, PCDC6 and PCDC6IP, are associated with PMID:35396512:MAT2A, which facilitates PDCD6 methylation and promotes cell growth under glucose deprivation in cervical cancer." (PMID 38283897, 2023). "MiR-101 suppression also accelerates cervical cancer cell proliferation by promoting the expression of methionine adenosyltransferase II Alpha (MAT2A)." (PMID 36497343, 2022). "Taken together, our results revealed that MAT2A facilitates methylation of PDCD6 at K90 site to promote cervical cancer growth under glucose deprivation mediated by AMPK activation." (PMID 35396512, 2022). "We conclude that MAT2A facilitates PDCD6 methylation to promote cervical cancer growth under glucose deprivation, suggesting the regulatory role of MAT2A in cellular response to nutrient stress and cervical cancer progression." (PMID 35396512, 2022). "The underlying mechanisms of methionine adenosyltransferase 2 A (MAT2A)-mediated cervical cancer progression under nutrient stress are largely elusive." (PMID 35396512, 2022). "In line with the results from in vitro study, the further clinical analysis indicates the MAT2A level is positively related to PDCD6 level in cervical cancer tissues." (PMID 35396512, 2022). "For example, The circular RNA hsa_circ_0007364 through inhibiting microRNA-101-5p activated methionine adenosyltransferase IIα (MAT2A) expression to improve cervical cancer progression." (PMID 34130593, 2021). "In our study, we demonstrated that MAT2A facilitates PDCD6 methylation that is critical for PDCD6 protein stability maintenance under glucose deficiency, and thereby suppresses cell apoptosis of cervical cancer cells." (PMID 35396512, 2022). "It was recognized that miR-101 could suppress the invasion ability of cervical cancer cells by inhibiting the expression of MAT2A." (PMID 36497343, 2022). "Thus, our findings support an anti-apoptotic role of PDCD6 in cervical cancer cells at glucose deficiency condition and highlight the positive relationship between PDCD6 and MAT2A during cervical cancer development." (PMID 35396512, 2022). "Furthermore, the clinical analysis indicates that the MAT2A protein level is positively associated with the PDCD6 level, and the high level of PDCD6 significantly correlates with poor prognosis and advanced stages of cervical cancer patients." (PMID 35396512, 2022). "The interaction between MAT2A and programmed cell death protein 6 (PDCD6) in cervical cancer cell lines was detected by immunoprecipitation, immunoblotting and mass spectrometric analysis." (PMID 35396512, 2022). "We also explored the effects of MAT2A and PDCD6 on cell viability and apoptosis in cervical cancer cells." (PMID 35396512, 2022). "A higher level of MAT2A protein was detected in MS751 and C33A cells compared with that in normal cervical epithelial cells (ECT1) and other cervical cancer cell lines." (PMID 35396512, 2022). "Our study will provide a novel mechanism by which MAT2A facilitates methylation of PDCD6 to promote cervical cancer growth, suggesting that MAT2A and PDCD6 might be the targets for cervical cancer therapy." (PMID 35396512, 2022). "Moreover, the protein level of MAT2A and PDCD6 in cervical cancer patients was validated using IHC analyses, and the clinicopathological characteristics were also analyzed." (PMID 35396512, 2022). "The CCK-8 and the AnnexinV/PI analyses together indicated that MAT2A depletion led to the impaired growth and enhanced apoptosis in MS751 cells under both normal and glucose deprivation conditions, revealing the promoting effect of MAT2A on growth of cervical cancer cells." (PMID 35396512, 2022).
glioma (5 papers, 2021 to 2026). A benign or malignant brain and spinal cord tumor that arises from glial cells (astrocytes, oligodendrocytes, ependymal cells). "PRMT5 and MAT2A show promise as a combined target in gliomas where 5′-methylthioadenosine phosphorylase (MTAP) deficiency accounts for approximately 30%." (PMID 40450009, 2025). "Histone methylation is promoted by MAT2A, and cells can be prompted to proliferate in a methionine-restricted environment, which is associated with the progression of glioma." (PMID 37114036, 2023). "Further validation using immunofluorescence and western blotting confirmed that PRMT5 and MAT2A were consistently overexpressed in glioma cell lines, supporting their potential as inhibitor targets in future studies." (PMID 40450009, 2025). "Tissue microarray analysis revealed that the extent of DAB staining for MTAP and PRMT5 was generally higher than that for MAT2A in glioma samples." (PMID 40450009, 2025). "This approach sets the stage for the further investigation of the therapeutic potential of targeting PRMT5 and MAT2A in glioma." (PMID 40450009, 2025). "MAT2A is an essential amino acid, and a high expression of MAT2A or an inhibitor of MAT2A can reduce the proliferation of glioma cells." (PMID 37114036, 2023). "By analyzing the RNA-seq data from the CGGA database, we found a higher level of MAT2A mRNA in WHO grade II/IV glioma than that in healthy brain." (PMID 39872059, 2023). "Western blotting, immunohistochemistry, quantitative real-time PCR, colony formation assays, and other experiments were used to verify the role of MAT2A in glioma genesis." (PMID 33859984, 2021). "This study explored the combined effects of PRMT5 and MAT2A inhibitors on glioma progression." (PMID 40450009, 2025). "The expression of MAT2A was positively correlated with World Health Organization-grade glioma." (PMID 33859984, 2021). "In glioma models, dual inhibition of PRMT5 and MAT2A produced a synergistic synthetic lethal effect, markedly suppressing tumour growth and prolonging survival." (PMID 41537447, 2026). "Our study proved the combination of PRMT5 and MAT2A inhibitors may induce synthetic lethality by downregulating the PI3K-AKT pathway, indicating the potential of this approach in treating gliomas." (PMID 40450009, 2025).